ARAF (A-Raf proto-oncogene, serine/threonine kinase)
Description:
Involved in the transduction of mitogenic signals from the cell membrane to the nucleus. May also regulate the TOR signaling cascade. Phosphorylates PFKFB2. [Isoform 2]: Serves as a positive regulator of myogenic differentiation by inducing cell cycle arrest, the expression of myogenin and other muscle-specific proteins, and myotube formation.
Synonyms: ARAF1; PKS2; A-Raf; RAFA1
Tractability: Small molecule: a drug acting on it is in phase 2 or 3 trials; a structure with a bound ligand is known; a high-quality ligand is known; it belongs to a druggable protein family. Antibody: the Human Protein Atlas places it where antibodies can reach. PROTAC: ubiquitination databases record sites on it; its protein half-life has been measured; a small molecule that binds it is known.
Target class: Kinase; Enzyme; TKL protein kinase RAF family; Protein Kinase; TKL protein kinase group
Gene: Protein-coding gene on chromosome X (47,561,182 to 47,571,921, forward strand). Ensembl gene ENSG00000078061.
Subcellular location (Human Protein Atlas): Plasma membrane
Pathways (Reactome):
Disease: Gain-of-function MRAS complexes activate RAF signaling; Paradoxical activation of RAF signaling by kinase inactive BRAF; SHOC2 M1731 mutant abolishes MRAS complex function; Signaling by BRAF and RAF1 fusions; Signaling by RAF1 mutants; Signaling by high-kinase activity BRAF mutants; Signaling by moderate kinase activity BRAF mutants; Signaling downstream of RAS mutants
Signal Transduction: MAP2K and MAPK activation; Negative regulation of MAPK pathway; RAF activation
Gene Ontology:
Molecular function: protein binding; protein serine/threonine kinase activity; MAP kinase kinase kinase activity; protein kinase activity; ATP binding; protein serine kinase activity
Biological process: negative regulation of apoptotic process; positive regulation of peptidyl-serine phosphorylation; regulation of proteasomal ubiquitin-dependent protein catabolic process; regulation of TOR signaling; MAPK cascade; protein modification process; signal transduction
Cellular component: plasma membrane; cytoplasm; cytosol; mitochondrion
Homologues: Orthologues: chimpanzee ARAF (100% identical), macaque ARAF (99% identical), dog ARAF (97% identical), rabbit ARAF (96% identical), pig ARAF (95% identical), mouse Araf (95% identical), guinea pig ARAF (95% identical), rat Araf (94% identical), tropical clawed frog araf (70% identical), zebrafish araf (67% identical). Paralogues in human: RAF1 (63% identical), BRAF (58% identical), KSR2 (22% identical), KSR1 (21% identical), MAP3K9 (20% identical), MAP3K10 (20% identical), TNNI3K (19% identical), MAP3K11 (19% identical), MAP3K21 (19% identical), LRRK2 (18% identical), MAP3K12 (17% identical), LIMK1 (17% identical), and 11 more.
Diseases named in the same sentence as ARAF in open-access papers:
ARAF is named in the same sentence as 85 diseases in open-access papers, as found by Europe PMC text mining. Sharing a sentence is not in itself a finding about the gene and the disease. The quoted sentences say what the papers report.
melanoma (17 papers, 2012 to 2025). A malignant, usually aggressive tumor composed of atypical, neoplastic melanocytes. "The second report showed that ARAF activating mutations confer both preclinical and clinical resistance to belvarafenib monotherapy in melanoma, where the resistance is dependent on kinase activity and dimer formation." (PMID 41023593, 2025). "Taken together, these data strongly supported that loss of BRAF and CRAF in NRAS-mutated murine melanoma cells induced resistances involving a compensatory effect of ARAF." (PMID 28497782, 2017). "ARAF/MITF complexes were found in the cytosol of NRAS-mutated mouse melanoma cells." (PMID 35091687, 2022). "ARAF might also be a therapeutic target in NRAS-mutated melanoma, as it was recently established that ARAF could mediate MAPK pathway activation under specific conditions in melanoma." (PMID 31398831, 2019). "Moreover, rare activating mutations of ARAF have been identified in melanoma associated with an NRAS mutation, reinforcing the potential role of ARAF in NRAS-induced melanoma." (PMID 31398831, 2019). "Taken together, these findings suggest that ARAF might be also an important player in NRAS-mutated melanoma under specific conditions." (PMID 28497782, 2017). "This is the case, for instance, in NRAS-mutated melanoma, in which RAF1 and BRAF compensate for each other, and ARAF compensates for the loss of both other isoforms in a mechanism that is still ERK-dependent." (PMID 37020037, 2023). "This suggests compensatory functions of other RAF proteins, such as the ones reported in NRAS-mutant melanoma, or a more specific function of ARAF, which is able to activate RAS by antagonizing NF1 binding." (PMID 37020037, 2023). "To better characterize the role of ARAF in NRAS-driven melanoma, we searched for new ARAF interactors by mass spectrometry." (PMID 35091687, 2022). "The potential role of ARAF in NRAS-induced melanoma was further strengthened by an in silico search in public databases that allowed to identify patients with metastatic melanomas harboring an ARAF mutation associated with activating NRAS mutations." (PMID 35091687, 2022). "The rationale for combining these drugs is that several proteins, which are linked to melanoma cell response and resistance to BRAFV600/MEK-targeting agents, are HSP90 clients including ARAF, CRAF, BRAFV600E, CDK4, COT, IGF1R, PDGFR-β and AKT." (PMID 30989459, 2019). "Several independent labs have demonstrated that melanoma can acquire resistance to vemurafenib in various ways, including mutation of NRAS, upregulation of CRAF or ARAF, redundant PI3-Kinase signaling or activation of COT." (PMID 23110092, 2012). "Indeed, based on mechanisms still unclear, melanoma cells show a dysregulated expression of the RAF isoforms ARAF and CRAF, which reactivate pERK1/2 playing a crucial role in the acquisition of resistance." (PMID 38493226, 2024). "Interestingly, point mutations in ARAF that confer resistance to belvarafenib have been identified both in model systems and in patients with BRAFV600E-driven melanoma treated with belvarafenib." (PMID 36963492, 2023). "In melanoma cells, ARAF or CRAF may be overexpressed, while BRAF is blocked." (PMID 32605090, 2020). "In BRAFi-resistant melanoma, the upstream reactivation of signal transduction from the cell membrane to MAPK/ERK kinases is caused by the overexpression of tyrosine kinase receptors, which leads to cell division by the activation of ARAF and CRAF kinases instead of BRAF." (PMID 32605090, 2020). "Reactivation of ERKs can also occur through enhanced RAF dimerization, a key mechanism of resistance to RAFi in melanoma, as well as the abnormal expression of other RAF isoforms, such as CRAF and ARAF." (PMID 39596009, 2024). "It was shown that NRAS mutant melanoma cells can keep their malignant properties after knockout of BRAF and CRAF, being dependent on ARAF to sustain ERK signaling." (PMID 37627277, 2023).
melanoma (continued). "The MITF transcription factor directly binds to the kinase domain of RAF kinases, including ARAF, BRAF and CRAF in melanoma cells." (PMID 35091687, 2022). "By investigating the role of ARAF in NRAS-driven mouse melanoma through mass spectrometry experiments followed by a functional siRNA-based screen, we unexpectedly identified MITF as a direct ARAF partner." (PMID 35091687, 2022). "With the activation of alternative isoforms of the RAF protein, BRAFV600E, melanoma treated with BRAF inhibitors can become resistant through flexible switching between RAF isoforms capable of ERK pathway signaling, increasing ARAF or CRAF expression." (PMID 32605090, 2020). "We demonstrated that ARAF, which had never been involved in melanoma so far, was responsible for MAPK activation and cell proliferation." (PMID 28497782, 2017). "The role of ARAF in NRAS-induced melanoma has not been a matter of intense investigation mainly because of the well-described paradoxical effects of RAF inhibitors in RAS-mutated tumours, which is thought to rely mostly on BRAF and CRAF dimerization." (PMID 28497782, 2017). "Interestingly, we demonstrated that in the absence of BRAF and CRAF, ARAF alone can sustain both ERK activation and proliferation in NRAS-mutated melanoma cells." (PMID 35091687, 2022). "BRAFV600E melanoma treated with BRAF inhibitors may acquire resistance through flexible switching between different RAF isoforms capable of reactivating the ERK pathway, upregulating ARAF or CRAF." (PMID 29100459, 2017). "Hence, targeting the positive feedback loop of p300-NONO-CRAF/ARAF-pERK1/2 may be an effective strategy to overcome the resistance of BRAF inhibitors for melanoma patients." (PMID 38493226, 2024). "Notably, NONO interacts with and stabilizes both ARAF and CRAF in melanoma cells; moreover, NONO is acetylated by p300 acetyltransferase, which stabilizes NONO antagonizing its ubiquitination/degradation." (PMID 38493226, 2024). "Interestingly, the NONO/ARAF/CRAF-mediated pERK1/2 activation leads to an increased expression of p300, which leads to increased acetylation and stability of NONO, thus sustaining a positive regulatory feedback loop in drug-resistant melanoma cells." (PMID 38493226, 2024).
lung carcinoma (10 papers, 2013 to 2025). "Given this promising clinical potential, the present study aimed to investigate the oncogenic potential and sorafenib response of ARAF p.S214C mutation in lung cancer further." (PMID 40647542, 2025). "This study shows that ARAF p.S214C mutation is a rare but important mutation that exhibits oncogenic properties in lung cancer models." (PMID 40647542, 2025). "Although ARAF mutations only constitute ~1.4% of lung cancers, with the ARAF p.S214C mutation occurring in ~0.03% of lung adenocarcinoma cases, our findings revealed the therapeutic potential of sorafenib in a distinct subgroup of patients." (PMID 40647542, 2025). "ARAF p.S214C-mutated lung cancer cells demonstrate remarkable sorafenib sensitivity in vitro and in vivo, which aligns with a previous clinical report of a lung cancer patient carrying this mutation being an exceptional responder to sorafenib." (PMID 40647542, 2025). "In this study, the oncogenic potential and sorafenib sensitivity of the ARAF p.S214C mutation were elucidated in lung cancer models." (PMID 40647542, 2025). "Notably, all ARAF p.S214 mutations in lung cancer occur in adenocarcinoma, underscoring the rarity yet the significance of this mutation in the most prevalent subtype of lung cancer." (PMID 40647542, 2025). "By characterizing the gene–drug sensitivity pair of ARAF p.S214C and sorafenib, this study may help establish ARAF p.S214C mutation as a novel biomarker for predicting sorafenib efficacy, which could implicate a new precision medicine strategy for lung cancer." (PMID 40647542, 2025). "Given that lung cancer is the most frequent type of cancer worldwide, with ~2.5 million new cases in 2022, an estimated 750 lung cancer patients per year may harbor the ARAF p.S214C mutation and could potentially benefit from sorafenib treatment." (PMID 40647542, 2025). "Importantly, this is the first study to systematically investigate the oncogenicity and sorafenib response of the ARAF p.S214C mutation in lung cancer." (PMID 40647542, 2025). "Fourth, this study only characterized the ARAF p.S214C mutation in the context of lung cancer." (PMID 40647542, 2025). "In conclusion, our study elucidates the oncogenic role of the ARAF p.S214C mutation in lung cancer and suggests the potential therapeutic avenue of its relationship with sorafenib, reinforcing the necessity of continuous research to refine patient stratification based on rare mutations." (PMID 40647542, 2025). "In addition, ARAF mutation has been discovered in lung cancer, and sorafenib, the RAF-targeted kinase inhibitor, improves the prognosis of advanced lung cancer patients." (PMID 36457747, 2022). "Importantly, one clinical study reported an exceptional response to sorafenib with near-complete tumor regression in a lung adenocarcinoma patient carrying an ARAF p.S214C mutation, highlighting the potential of ARAF mutations in contributing to sorafenib sensitivity in lung cancer." (PMID 40647542, 2025). "Notably, this study may provide strong scientific evidence to establish the ARAF p.S214C mutation as a novel biomarker for predicting sorafenib’s efficacy in lung cancer and inform future clinical trials aiming to evaluate the sorafenib responses in ARAF-mutated lung cancer patients." (PMID 40647542, 2025). "Not only were we surprised by the different regulatory mechanisms of ARAF with respect to the ERBB3-AKT signaling axis, but also by the observation that ARAF, previously classified more as an oncogene, acts as a tumor suppressor in a subset of lung cancers." (PMID 35938171, 2022). "ARAF is a highly conserved serine/threonine kinase that controls ERBB3 expression in lung cancer, thereby inhibiting AKT activation and subsequently inhibiting tumor metastasis." (PMID 36457486, 2022). "In a study, ARAF was determined to be required for MAPK activation in a cell-type-dependent manner in the case of A549 lung cancer cells and ARAF-knockdown cells." (PMID 31652660, 2019).
lung carcinoma (continued). "While most studies have focused on BRAF and CRAF, the pathological significance of ARAF in lung cancer remains unclear." (PMID 40647542, 2025). "Moreover, the suppression of ERBB3-AKT-driven lung cancer spreading requires both kinase-dependent and independent functions of ARAF." (PMID 35938171, 2022). "Other studies reported that ARAF mutations could drive lung cancer and that the RAF-targeted kinase inhibitor sorafenib improved the prognosis of advanced lung cancer patients, thus providing a new opportunity for lung cancer treatment." (PMID 32923479, 2020). "We extended the study to three lung cancer cell lines used in the co-IP experiments and assessed the effects of each RAF inhibitor on endogenous ARAF, BRAF, and CRAF kinase activity." (PMID 41282105, 2025). "RAF inhibitors were demonstrated to have the capacity to induce homodimerization of ARAF and heterodimerization of BRAF with CRAF and the scaffolding protein KSR1 in lung cancer cells." (PMID 31652660, 2019). "This study revealed a novel function for ARAF, which, once in dimer form, activates the MAPK cascade with an impact on sustaining lung cancer cell invasion." (PMID 31652660, 2019). "Of these fusions, 16 (including ALK, ARAF, BRAF, FGFR1, FGFR3, RET, and ROS1) and 21 (including ABL1, GNAS, JAK2, and NRG1) were classified as either related to lung cancer, or as oncogenes that have not been reported in lung cancer, respectively." (PMID 36153311, 2022).
lung adenocarcinoma (9 papers, 2015 to 2026). A carcinoma that arises from the lung and is characterized by the presence of malignant glandular epithelial cells. "Previous clinical research showed that a ARAF p.S214C mutation exhibited exceptional responsiveness to sorafenib in lung adenocarcinoma." (PMID 40647542, 2025). "Here, using lung adenocarcinoma cell lines and animal models, it is demonstrated that the ARAF p.S214C mutation is associated with enhanced oncogenic signaling and sensitivity to sorafenib." (PMID 40647542, 2025). "Mutations in ARAF have been linked as oncogenic drivers in lung adenocarcinoma, and are exceedingly rare in CRC and comprise approximately 2% of cases in the CRC dataset from TCGA." (PMID 28178681, 2017). "Imielinski and colleagues reported that oncogenic and sorafenib-sensitive ARAF mutations were present in 1% of lung adenocarcinoma cases in the TCGA samples." (PMID 26486077, 2015). "Such analysis identified oncogenic ARAF mutations in a lung adenocarcinoma patient with near complete radiographic response for 5 years to single agent sorafenib." (PMID 26275293, 2015). "In support of this, ARAF dimers have been found to promote ERK signaling and cell cycle arrest in KRAS-mutated, RAF1-deficient lung adenocarcinoma cell lines." (PMID 37020037, 2023). "In addition, mutant ARAF is found to be an oncogenic driver in lung adenocarcinoma and can be used as an indicator of sorafenib response." (PMID 38217548, 2024). "On the other hand, ARAF is a known proto-oncogene and member of the MAPK cascade which is frequently mutated in lung adenocarcinoma and its inhibition is a promising therapeutic target and thus its targeting by tRF-3021a could possibly be associated with cancer progression." (PMID 33092114, 2020). "ARAF p.S214C mutant, ARAF wild-type (WT), and EGFP control genes were ectopically expressed in lung adenocarcinoma cell lines retroviral transduction." (PMID 40647542, 2025).
breast carcinoma (8 papers, 2013 to 2024). "ARAF, also required for MAPK activation in a variety of cancer types (e.g., colorectal, pancreatic, and breast cancers), is associated with the migration and invasiveness of tumor cells." (PMID 39136575, 2024). "In 2014, a study demonstrated that ARAF was required for MAPK activation in a variety of cancer types (e.g., colorectal, pancreatic, and breast cancers) and further verified that ARAF enhanced the migration and invasive ability of these tumor cells." (PMID 32923479, 2020). "Recent studies have indicated that ARAF required for MAPK activation enhances the migration and invasive ability of various cancer types, such as colon cancer, pancreatic cancer and breast cancers." (PMID 36457747, 2022). "For breast cancer, of the six predicted candidates (PRKCQ, ARAF, MAPK14, BRMS1, CDC42BPA, SP3), three (PRKCQ, ARAF, MAPK14) are members of at least one KEGG cancer relevant pathway." (PMID 25961669, 2015). "ARAF, a member of the RAF kinase family, is involved in tumor development by activating mitogen-activated protein kinase (MAPK) in various malignancies including lung, colorectal, pancreatic, and breast cancers." (PMID 35865472, 2022). "ARAF is a member of the RAF kinase family that is necessary for mitogen-activated protein kinase (MAPK) activation in various malignancies, including lung, colorectal, pancreatic, and breast cancers." (PMID 32923479, 2020).
bladder cancer (6 papers, 2011 to 2025). "The KEGG bladder cancer pathway activation in poor prognosis CRCs was mostly due to increased expression of functional nodes HRAS/KRAS/NRAS, ARAF/BRAF/RAF1, MAPK1/MAPK3, and RPS6KA5." (PMID 36316649, 2022).
glioma (5 papers, 2014 to 2023). A benign or malignant brain and spinal cord tumor that arises from glial cells (astrocytes, oligodendrocytes, ependymal cells). "Differential expression was found, however, with increased mean RAF1 transcripts and MAPK1 abundance and decreased mean ARAF transcripts in IDH-mutant gliomas; yet only low ARAF expression correlated with improved patient survival." (PMID 27852048, 2017). "The upregulated gene, CDK4, acts downstream of Raf and regulates cell proliferation; thus, increased CDK4 expression may negate the inhibition of cell proliferation resulting from downregulation of ARAF, leading instead to the survival of glioma cells." (PMID 25007077, 2014). "ARAF takes part of the RAS-MAPK pathway being activated by EGF/EGFR activation and supporting invasiveness of gliomas." (PMID 27613830, 2017).